HMGB1 (high mobility group box 1)
Diseases named in the same sentence as HMGB1 in open-access papers (continued):
Sharing a sentence is not in itself a finding about the gene and the disease.
COVID-19 (continued). "Consistent with a previous literature, the IL-6 increase in COVID-19 severe patients should be related to HMGB1 macrophage release, but further investigations are needed." (PMID 32724296, 2020). "In severe COVID-19 patients, multiple DAMPs, including HMGB1 and S100 proteins, are significantly increased due to the massive release of inflammatory mediators and the occurrence of cell death, thereby causing the body's immune response disorders and aggravating the progression of COVID-1921." (PMID 38600309, 2024). "During the COVID-19 pandemic, HMGB1 was identified as a potential therapeutic target for COVID-19-related lung injury and could also serve as a key cytokine for predicting ARDS severity." (PMID 39479463, 2024). "HMGB1 is a central mediator of lethal inflammation and could be a potential target for innovative therapeutic strategies for COVID-19, even in the pediatric field." (PMID 36944948, 2023). "The serum HMGB1 in COVID-19 patients is increased and positively correlated with disease severity." (PMID 37256223, 2023). "Interestingly, an upregulation of the receptor for advanced glycation end products (RAGE) and HMGB1 is also found among patients with the most severe forms of COVID-19, which indicates the harmful effects of augmented HMGB1 in respiratory viral infections." (PMID 37798799, 2023). "An original finding of our study was the association of HO-1 with HMGB1 levels, suggesting that targeting the HO-1/HMGB1 relationship may provide a new line of support against the transition from mild/moderate to severe COVID-19 development." (PMID 37685970, 2023). "Herein, the refractory respiratory failure in patients with COVID-19 was associated with increased CRP, D-dimers, LDH, Ferritin, HMGB1, and IL-33, as well as higher numbers of circulating neutrophils, higher plasma levels of IL-6 and IL-10, and diminished numbers of lymphocytes and platelets." (PMID 37604833, 2023). "Therefore, the detected HMGB1 levels in mild to moderate COVID-19 patients at hospital admission most likely reflect the activity of the innate immune system and represent a framework of levels within which disease can be controlled." (PMID 37685970, 2023). "In addition to the HMGB1 protein, the recent literature indicates that serum levels of heme oxygenase-1 (HO-1) should also be determined in COVID-19 patients because it can prevent the consequences of hemolysis." (PMID 37685970, 2023). "HMGB1 may be involved in COVID-19 through at least two mechanisms: the TLR4-mediated cytokine storm in immune cells and RAGE-mediated ACE2 expression in alveolar epithelial cells." (PMID 37176041, 2023). "Additionally, the HMGB-1 levels were significantly elevated in the severe COVID-19 animal model versus the other two groups." (PMID 36507222, 2023). "HMGB1 is found in high concentrations in the serum of patients with severe COVID-19." (PMID 37256223, 2023). "HMGB1 may be a potential therapeutic target in severe cases of COVID-19, and HMGB1 inhibitors can represent promising drug candidates for the treatment of patients suffering from the disease." (PMID 35454134, 2022). "In this review, we briefly explain the role of HMGB1 in the cell, and particularly the involvement of extracellular HMGB1 (released from the cells) in inflammation-mediated diseases, with an emphasis on COVID-19." (PMID 35454134, 2022). "Since HMGB1 was further shown to promote expression of SARS-CoV-2 entry receptor ACE2 in alveolar epithelial cells, targeting HMGB1 by pharmacological inhibition might be a potential treatment option for COVID-19 patients." (PMID 33982161, 2022). "Severe COVID-19 patients were shown to have higher expression of the alarmin nuclear protein High mobility group box 1 (HMGB1), antiviral molecules like ISG-15 and LL-37, or functionally active tissue factor (TF) as protein cargo in NETs, produced mostly by normal density granulocytes (NDG)." (PMID 35720378, 2022).
COVID-19 (continued). "HMGB1 could play a key role in regulating the inflammatory response in COVID-19 by promoting SARS-COV-2 replication." (PMID 35454134, 2022). "Thus, in addition to HMGB1, other factors, such as different cytokines and alarmins, need to be observed in COVID-19 patients in order to develop effective tools for monitoring disease progression and outcome predictions." (PMID 35454134, 2022). "Circulating NETs in COVID-19 sera contain LL-37-DNA and high-mobility group box 1 (HMGB1)-DNA." (PMID 35327504, 2022). "Considering that SARS-CoV-2 might initiate inflammatory processes and induce ALI, HMGB1 could be used as a target for specific prevention and treatment option for pediatric COVID-19 and SARS-CoV-2-induced ALI." (PMID 35633962, 2022). "In COVID-19 patients, serum HMGB1 levels increase with disease severity." (PMID 36017003, 2022). "Thus, the median level of HMGB1 in children with MIS-C was significantly higher than in patients with post-COVID-19 and controls." (PMID 35558368, 2022). "On the other hand, those in the ICU (severe COVID-19) had both calprotectin and HMGB1 raised." (PMID 33672040, 2021). "Our results show that both HMGB1 and IL‐6 are important biomarkers of disease severity in COVID-19 and could guide early recognition of the most severe patients at the moment of ICU admission." (PMID 33939645, 2021). "Patients with critical COVID-19 had a higher amount of circulating NE-DNA and HMGB1-DNA complexes." (PMID 34685525, 2021). "Also, additional “inflammaging” markers like NLPR3 activation, IL-6, IL-12 and IL-1ß secretion, and danger-related molecular patterns, including high mobility group box 1 (HMGB1) have shown to be predictive for a severe COVID-19 course in elderly." (PMID 34680460, 2021). "A recent study showed that HMGB1 strongly correlates with mortality in COVID-19 patients." (PMID 33658363, 2021). "Extracellular HMGB1 may be an attractive potential therapeutic target for severe lung inflammation such as COVID-19." (PMID 34177566, 2021). "HMGB1 triggers toll-like receptor-4, generating the release of pro-inflammatory cytokine including IL-6, which is one of pathophysiological hallmarks of the cytokine storm in critically ill COVID-19 patients." (PMID 33939645, 2021). "Therefore, it is not surprising that other molecules associated with a damage-associated molecular pattern like high mobility group box 1 (HMGB1) are elevated in severe COVID-19 patients." (PMID 34445140, 2021). "The levels of serum HMGB1 in patients with severe COVID-19 obviously increased." (PMID 34446699, 2021). "HMGB1 and IL-6 levels were elevated in COVID-19 patients (n = 60) compared with healthy subjects." (PMID 33939645, 2021). "The mechanism by which SARS-CoV-2 induces HMGB1 release in COVID-19 remains unknown, although new evidence suggests that toll-like receptor 4 (TLR4) signaling may play a role in this process." (PMID 34616852, 2021). "Circulating NETs containing ISG-15, LL-37, and HMGB1 are detected in patients with COVID-19." (PMID 34685525, 2021). "The crosstalk between RAGE and TLR4 in response to DAMPs is underlined by the fact that RAGE-positive, TLR4 KO peritoneal macrophages produced almost no proinflammatory cytokines in response to HMGB1, suggesting the existence of a HMGB1/RAGE/TLR4 axis in mediating inflammation in COVID-19." (PMID 34204735, 2021). "However, it should be noted that chloroquine, currently used in COVID-19 therapy, inhibits HMGB1 release especially in DM patients." (PMID 32760352, 2020). "In summary, HMGB1 may be involved in COVID-19 through at least two mechanisms: one is TLR4-mediated cytokine storm in immune cells, and the other is AGER-mediated ACE2 expression in alveolar epithelial cells." (PMID 33313438, 2020). "Serum HMGB1 in severe COVID-19 patients is elevated (189.40 ± 140.88 ng/ml)." (PMID 33313438, 2020). "In contrast, TLR4 may contribute to the cytokine release (e.g., TNF) induced by HMGB1 in immune cells, which is also related to COVID-19." (PMID 33313438, 2020).
COVID-19 (continued). "Given that HMGB1 is a potential target for SARS, we therefore hypothesize that HMGB1 may play a similar pathogenic role in COVID-19 by mediating inflammation and immune dysfunction." (PMID 32442210, 2020). "Thus, HMGB1 inhibitors are likewise promising drug candidates for the treatment of patients suffering from COVID-19." (PMID 33313438, 2020). "Consistent with this idea, our current study shows that compared with healthy controls, the serum HMGB1 levels in some severe COVID-19 patients are significantly increased, indicating that there may be a pathological link between HMGB1 and COVID-19." (PMID 33313438, 2020). "In fact, HMGB1 or NETs could serve as potential targets for therapies in coronavirus disease (COVID-19)." (PMID 33392206, 2020). "The finding of increased NETs in ventilated severe COVID-19 patients may be both a consequence and a trigger of HMGB1 release in a dangerous self-perpetuating loop." (PMID 32724296, 2020). "In this study, we provide evidence that HMGB1 could be a biomarker and therapeutic target for severe COVID-19." (PMID 33313438, 2020). "Further studies are actually needed to ascertain whether plasma levels of AGEs, sRAGE, HMGB1, and S100 proteins in DM COVID-19 patients are differentially affected by conventional vs. intensive insulin therapy and are predictive of patients' outcome." (PMID 32760352, 2020). "In addition, serum high-mobility group box 1 (HMGB1), a damage-associated molecular pattern and a mediator of severe inflammation, has been described to be elevated in severe COVID-19 patients and proposed as a marker of COVID-19 cytokine storm in immune cells." (PMID 38673677, 2024). "Therefore, HMGB1 is considered to be a potential therapeutic target for COVID-19 and CKD." (PMID 37256223, 2023). "Our study suggests that HMGB1 and HO-1 in serum could be useful inflammatory indicators in the early stage of COVID-19 infection and could be included in the classification criteria of COVID-19 patients on hospital admission." (PMID 37685970, 2023). "Therefore, we assessed whether the inhibition of one of the DAMPs, HMGB-1, attenuated alveolar tissue injury in a severe COVID-19 animal model." (PMID 36507222, 2023). "Moreover, the analysis of correlations among these biomarkers in the serum of patients with COVID-19 demonstrated that HMGB-1 levels were most strongly correlated with levels of total epithelial cell death marker, M65 (correlation coefficient = 0.612, p < 0.0001)." (PMID 36507222, 2023). "Because extracellular HMGB1 is strongly associated with the clinical severity of COVID-19, leytragin-induced SIRT1 activation may contribute to the development of HMGB1-targeting therapeutics and thus to the prevention of the cytokine storms that often accompany COVID-19." (PMID 36139497, 2022). "Similarly, HMGB1 was detected in only 58% of healthy donors and in 74% of COVID-19 patients." (PMID 35663992, 2022). "Also, a recent study reported increased HMGB1 levels in serum of COVID-19 patients." (PMID 34539644, 2021). "Indeed, HMGB1 is elevated in COVID-19 patients and could be an additional potential biomarker of the disease progressing to a more severe form." (PMID 34395368, 2021). "Therefore, HMGB1 could be a key player in the development of severe and long-lasting COVID-19 headache." (PMID 34384355, 2021). "However, the molecular identity of D in the context of COVID-19 (which, in our model, stimulates I), is as yet unknown, though some have speculated that HMGB1 might play this role." (PMID 34777366, 2021). "Thus, HMGB1 may occupy a central place in COVID-19 pathology, both as an extracellular alarmin and as an intracellular regulator of transcription." (PMID 34108245, 2021). "In addition, HMGB1 levels are elevated in COVID-19 patients and therefore could be a novel biomarker in managing COVID-19." (PMID 34395368, 2021).
COVID-19 (continued). "ELISA measurement of systemic HMGB1 levels in some other clinical conditions including active systemic lupus erythematosus (SLE) or septic shock has previously been reported to underestimate results reminding of the problems that we encountered in our pilot study in COVID-19 patients." (PMID 34943830, 2021). "Here, we report that high mobility group box 1 (HMGB1), a prototypical damage-associated molecular pattern (DAMP) and a central mediator of lethal inflammation, could be a potential target for innovative therapeutic strategies for COVID-19." (PMID 33313438, 2020). "We further investigated the extracellular high-mobility group box 1 (HMGB1) pathway due to previous reports implicating this protein as a prospective biomarker and therapeutic target of COVID-19 severity." (PMID 38172612, 2024). "Our data demonstrated that serum biomarkers HMGB1, myoglobin, FABP3 and troponin I were significantly altered during the initial phase of COVID-19." (PMID 37662953, 2023). "The lung and spleen tissue obtained from patients who died from COVID-19 exhibited higher densities of cells expressing NLRP3, IL-18, NF-κB and gasdermin D, and even HMGB-1, than age-matched controls who had died unexpectedly, but free of SARS-CoV-2-infection." (PMID 38439942, 2023). "Sustained platelet activation in COVID-19 boosts the release of PF4 and HMGB-1, inducing neutrophil activation and the release of NETs, which strongly promote coagulation." (PMID 38069209, 2023). "In our study, we evaluated the levels of HMGB1 protein in the sera of children with MIS-C, patients with a recent history of COVID-19, and healthy children." (PMID 35558368, 2022). "Extracellular HMGB-1 regulates delayed innate immune responses and provides a biomarker for predicting the development of ARDS due to COVID-19." (PMID 35204430, 2022). "The results showed an evidently more increased expression of the HMGB1 band in patients with MIS-C, compared both with post patients with COVID-19 and controls." (PMID 35558368, 2022). "Similar to COVID-19 patients, LA treated mice had higher soluble ICAM-1, and DAMPs (i.e., ds-DNA, HMGB-1, and histone-DNA complex levels) which as we shall discuss later can be pro-thrombotic and pro-inflammatory." (PMID 35502320, 2022). "Following NLRP3 inflammasome action is the downstream release of DAMPs (i.e., the excess release of nuclear protein high-mobility group box 1 (HMGB1]) through GSDMD, as demonstrated by the hyperinflammation during viral infection and/or COVID-19." (PMID 35328506, 2022). "In this investigation, we tested HMGB1 expression by Western blot in sera from children with MIS-C, compared with children post COVID-19 and healthy donors." (PMID 35558368, 2022). "Taken all the data together, we found significant elevations of circulating HMGB1, NLRP3 and IL6 levels in COVID-19 patients with headache compared to COVID-19 patients without headache." (PMID 34384355, 2021). "Thus, the modulation of HMGB1 release may be vital for treating COVID-19." (PMID 34616852, 2021). "Therefore, we suggest that HMGB1, released mainly from respiratory infection in COVID-19 may convey the damage signal to the trigeminal neurons in the ganglia and trigeminal perivascular nociceptors within the dura mater and activate the trigeminal system through pattern recognizing receptors." (PMID 34384355, 2021). "Within this cohort of severe COVID-19 patients admitted in ICU, HMGB1, and IL-6 plasma concentrations measured at ICU admission were highest in patients with a fatal course of the disease." (PMID 33939645, 2021). "DAMPs, such as HMGB1, S100A8/A9 and SP-A, are elevated in COVID-19 patients compared to healthy subjects." (PMID 34680058, 2021). "In addition to IL-6, HMGB1 might also be a potential therapeutic target in severe COVID-19." (PMID 33939645, 2021).
COVID-19 (continued). "In addition, elevated levels of circulating TLR4 DAMPs in COVID-19 patients (beta-defensin-3; fibrinogen; heat-shock protein 70; HMGB1; syndecan; S100A8/9; and surfactant A and D) may be responsible for the feed-forward loop of the persistent inflammation, resulting in cytokine storm." (PMID 33498183, 2021). "In HNECs treated with HMGB1 and OSM, upregulation of the COVID-19-related genes TMPRSS6, furin, and cathepsin L (CTSL) is observed." (PMID 34445093, 2021). "In HNECs treated with HMGB1 and OSM, upregulation of the COVID-19-related genes TMPRSS6, furin, and cathepsin L (CTSL) was observed compared to the control, while no change of ACE2 or TMPRSS2 was observed." (PMID 34445093, 2021). "Thus, it could be hypothesized that the upregulation in TLR downstream signaling molecules could be due to increased TLR/MyD88/NF-kB pathway in COVID-19 patients, of which TLR1 and 6 may participate through activation caused by beta-defensin-3, HMGB1 and S protein oligomannose-type glycans." (PMID 33498183, 2021). "So far, it is the first clinical study investigating the role of circulating inflammatory and nociceptive molecules such as HMGB1, NLRP3 inflammasome, IL-6, IL-10, angiotensin II, and ACE2 in COVID-19 headache." (PMID 34384355, 2021). "The life-threatening inflammation in severe COVID-19 is likewise sustained by a cytokine storm and strongly increased systemic levels of ferritin, LDH and HMGB1 represent additional common denominators." (PMID 33975537, 2021). "This study investigated two prognostic biomarkers, the high mobility group box 1 (HMGB1) and interleukin-6 (IL-6), in patients with severe COVID-19 at the time of admission in the intensive care unit (ICU)." (PMID 33939645, 2021). "Nonetheless, we were able to corroborate that LL-37, HMGB1 and ISG-15 are expressed in NETs from COVID-19 patients by confocal microscopy." (PMID 34685525, 2021). "ROC for inflammatory markers indicated the significant role of HMGB1, NLRP3, IL-6 and ACE2 in discriminating the presence of headache in patients with COVID-19." (PMID 34384355, 2021). "A similar process has been postulated for HMGB1 and SARS-CoV-2 RNA fragments contributing to hyperinflammation in COVID-19." (PMID 34444232, 2021). "HMGB1 as a prototypical DAMP represents a critical marker of intense inflammation and studies have shown that serum HMGB1 is increased in COVID-19 cases and positively correlated with disease severity." (PMID 34384355, 2021). "Thus, the functional role, expression level, modification status, redox status, and localization of HmgB1 are all subject to further studies, which, from our prospective, are of great importance with the regard to treatment of multiple diseases, including COVID-19." (PMID 33114717, 2020). "HMGB1 is a crucial mediator of systemic inflammatory response, and observational studies from Brazil have shown that SARS-CoV-2 infection induces the upregulation of HMGB1 in patients with the most severe forms of COVID-19(Coronavirus disease 2019)." (PMID 38740617, 2025). "In this retrospective cross-sectional study, we found that serum concentrations of high-mobility group box 1 (HMGB1) and heme oxygenase-1 (HO-1), at the time of hospital admission, could be useful biomarkers for COVID-19 management." (PMID 37685970, 2023). "summarized that high levels of HMGB1 are synonymous with disease severity, development of cytokine storm (CS), acute lung injury and acute distress syndrome (ARDS), and it is a potential prognostic factor for severe COVID-19 and mortality." (PMID 37662953, 2023). "NRP1 and high mobility group box 1 (HMGB1) help bind ACE-2 and COVID-19." (PMID 36979225, 2023). "CD15 + cells may undergo necrosis during COVID-19 CPE, thus shedding NETs that contribute to the HMGB1 increase." (PMID 37592135, 2023). "We found that EVs from COVID-19 patients carry CRP, PF4, and HMGB-1 on their surface, which may further fuel immunothrombosis." (PMID 38069209, 2023).